RNU6-647P (RNA, U6 small nuclear 647, pseudogene)
Gene: Small nuclear RNA gene on chromosome 2 (32,214,456 to 32,214,562, reverse strand). Ensembl gene ENSG00000201113.
Homologues: Orthologues: chimpanzee U6 (98% identical), rabbit U6 (93% identical), macaque U6 (93% identical), guinea pig U6 (90% identical), dog U6 (86% identical), pig U6 (86% identical), rat LOC120097308 (85% identical). Paralogues in human: RNU6-19P (93% identical), RNU6-12P (92% identical), RNU6-13P (92% identical), RNU6-166P (92% identical), RNU6-25P (92% identical), RNU6-26P (92% identical), RNU6-31P (92% identical), RNU6-32P (92% identical), RNU6-41P (92% identical), RNU6-1 (91% identical), RNU6-1175P (91% identical), RNU6-11P (91% identical), and 1289 more.